CX3CR1 (C-X3-C motif chemokine receptor 1)
Diseases named in the same sentence as CX3CR1 in open-access papers (continued):
Sharing a sentence is not in itself a finding about the gene and the disease.
tumor (375 papers, 2007 to 2026). "Cx3cr1 deficiency significantly suppressed intraperitoneal tumor growth, reduced ascitic fluid volume, and prolonged survival." (PMID 42279436, 2026). "Co-expression of CX3CL1 and CX3CR1 by tumor cells was significantly associated with longer disease-free and disease-specific survival." (PMID 40508161, 2025). "For instance, CD62L/CD62L ligands, CCR2/CCL2, VEGF receptor R1/VEGF-A, and CX3CR1/CX3CL1 receptor-ligand pairs have been most prominently associated with the recruitment of monocytes to the tumor microenvironment." (PMID 41440002, 2025). "Overall, these data support the model of Vhl deficiency–driven upregulation of the CX3CL1/CX3CR1 axis engagement as a mechanism that leads to increased myeloid infiltration and a distinct tumor-promoting inflammatory TAM state in the TME of RCC." (PMID 38618956, 2024). "The pathway of negative regulation for transforming growth factor beta (TGF-β) was enriched in SF1-lineage-associated CX3CR1+ macrophages and helped control the tumor growth." (PMID 38658971, 2024). "CX3CR1 was primarily expressed on myeloid-derived suppressor cells and tumor-associated macrophages." (PMID 38433196, 2024). "For example, CX3CR1 signaling enhances the accumulation of tumor-associated microglia/macrophages and angiogenesis during the progression and malignant transformation of low-grade gliomas." (PMID 38731899, 2024). "Our results suggest that CX3CR1+ cells are associated with an acute inflammatory response, tumor-promotion, and recurrence." (PMID 38433196, 2024). "Although we prepared both Opening and Closure samples, CX3CR1 expression in Closure samples was associated with various blood parameters and a tumor-promoting status." (PMID 38433196, 2024). "CTHRC1 not only interacts with the integrin β3‐Akt signaling pathway to increase myometrial invasion in the tumor microenvironment of EC but also promotes M2‐like tumor‐associated macrophage (TAM) invasion by increasing the expression of CX3CR1 in macrophages." (PMID 38466034, 2024). "High CX3CR1 expression and perineuronal infiltration are associated with local and early tumor recurrence." (PMID 38640310, 2024). "Our analysis identified CX3CR1+ monocytes as associated with anti-tumor activity, and another immunosuppressive VEGFA+ monocytes as associated with poor response." (PMID 36869384, 2023). "Expression of several other genes upregulated by ruxolitinib such as Csf2, Cx3cl1, Cx3cr1, Has1, and Ccl22 in myeloid cell populations is known to be associated with tumor progression, myeloid cell accumulation, and tumor progression." (PMID 37005447, 2023). "Studies have shown that MDSCs recruited to the tumor microenvironment mature into tumor-associated macrophages that lose expression of Ly6C, gain expression of F4/80 and Cx3Cr1, and maintain expression of IL-10 and PD-L1." (PMID 38094302, 2023). "In preclinical models, we evaluated TCR clonality in peripheral CX3CR1+ CD8+ T cells only in highly-mutated MC38 tumor-bearing mice treated with combined anti-CTLA-4/PD-L1 blockade therapy." (PMID 33658501, 2021). "Increased expression of CX3CL1 causes homing of anti-tumor cells of the immune system that express CX3CR1." (PMID 32466280, 2020). "Another study demonstrated that CTHRC1 expression has a role in tumor-associated macrophages infiltration by upregulating fractalkine chemokine receptor (CX3CR1) expression." (PMID 33628726, 2020). "This latter was based on the increased CX3CL1 expression on inflamed blood vessels of mouse lung after intravenous injection of tumour cells, as well as some known deficiencies of CX3CR1−/− mice." (PMID 29367702, 2018). "Homozygous loss of Cx3cr1 resulted in a significant decrease in tumor latency and in increased tumor incidence." (PMID 25987130, 2015). "In prostate cancer and pancreatic ductal adenocarcinoma, cancer metastasis is associated with CX3CR1 on tumor cells and the ligand CX3CL1 at metastasis site." (PMID 25110692, 2014).
tumor (continued). "In summary, we identified the role for CX3CR1 in macrophages that can promote tumor metastasis and is associated with poor cancer prognosis by contributing to angiogenic macrophage survival." (PMID 24245985, 2013). "The association between the increased expression of CX3CR1 and clinical stage, metastasis, and recurrence suggests its potential utility as an independent or supplementary biomarker in the prediction of tumor prognosis." (PMID 24245985, 2013). "To our knowledge we are the first to show that diclofenac causes pronounced arginase activation in tumor stroma CX3CR1 + cells, in peritoneal macrophages and in WBC." (PMID 20856806, 2010). "CX3CL1 encodes a secreted protein called fractalkine that recruits CX3CR1-expressing natural killer and T lymphocytes to the tumor microenvironment, thereby promoting natural killer-dependent antitumor responses in vivo." (PMID 18030354, 2007). "Thus, transferring CX3CR1high monocytes into CX3CR1-deficient (Cx3cr1−/−) mice prevents tumor invasion and reduces tumor metastasis to the lungs." (PMID 40427136, 2025). "We have recently demonstrated that immunosuppressive, IL17-secreting γδ T cells recruited to the tumor microenvironment by a CCL2-dependent mechanism upon CDK4/6 inhibition can repolarize tumor-associated macrophages toward a CX3CR1+ phenotype associated with resistance to therapy." (PMID 40662849, 2025). "Notably, one study revealed increased survival in patients (n = 45) with the presence of a common CX3CR1 V249I polymorphism, which correlated with reduced tumor vessel density and reduced M2 macrophage infiltration." (PMID 38731899, 2024). "Tumor-associated microglia downregulated CX3CR1 but upregulated CD112, CD58 and CD33." (PMID 38123840, 2024). "The activation of CX3CL1 (chemokine C-X3-C motif ligand 1, also known as fractalkine)/CX3CR1 (CX3C chemokine receptor 1) in tumor-associated microglia/macrophages (TAMs) increases the adhesion/migration capacity of GBM cells through the expression of MMP-2, -9, and -14." (PMID 37108208, 2023). "CX3CL1 may also promote the adhesion of CX3CR1-positive tumor cells to target organs, thus causing the migration of tumor cells and promoting tumorigenesis." (PMID 37770496, 2023). "Notably, a polymorphism in the CX3CR1 gene has been associated with reduced tumor infiltration by MG which led to increased survival of GBM patients." (PMID 33117364, 2020). "Similarly, CX3CR1 deficiency in the environment significantly suppresses macrophage accumulation, tumor growth and metastasis." (PMID 30237497, 2018). "We posited that regulation of FA uptake may be one of the underlying reasons for reduced tumor burden in groups with reduced CX3CR1." (PMID 29712888, 2018). "Next we analyzed whether the amount of Ly-6Chi monocytes in the blood changes over the course of disease progression in host Cx3cr1-deficient tumor-bearing mice, potentially contributing to their increased density in tumors." (PMID 25987130, 2015). "Next we evaluated whether the shorter survival times of tumor-bearing mice in the Cx3cr1-deficient background might result from tumor location or size at the end-point of survival." (PMID 25987130, 2015). "Our results showed that CX3CR1 deficiency impaired tumor angiogenesis in metastatic foci." (PMID 24245985, 2013). "Therefore, CX3CR1 is responsible for promoting macrophage survival within the tumor microenvironment, which is typically associated with TAMs that contribute to tumor development." (PMID 24245985, 2013). "We investigated whether the decreased metastatic ability of tumor cells in CX3CR1−/− mice could be caused by inhibition of angiogenesis." (PMID 24245985, 2013). "Therefore, simultaneous increases in sFKN and CX3CR1 expression may be responsible for the pro-tumor effect of the FKN/CX3CR1 axis, which increases the risk of metastasis." (PMID 38731899, 2024).
tumor (continued). "Nevertheless, it is important to note that the upregulation of CX3CR1 expression may be associated with increased expression of this protein on the tumour cells, which may result in metastasis when the cancer cells enter the bloodstream and bind CX3CR1 on endothelial cells." (PMID 39011040, 2024). "By our comparative approach, the data hint toward a pro-tumorigenic Siglec10+CX3CR1+ macrophage population depending on the characteristic tumor microenvironment (TME) of highly malignant GBMs." (PMID 42003504, 2026). "Mechanistically, effective anti-PD-1 therapy revitalizes anti-tumor immunity by specifically promoting the proliferation and maintaining the function of these CX3CR1+ effector cells within the tumor." (PMID 41929510, 2026). "On the other hand, the CX3CL1/CX3CR1 axis promotes cancer cell proliferation, migration, and invasion, recruits pro-tumor immune cells, and promotes tumor angiogenesis through TAMs." (PMID 41445742, 2025). "Specifically, an increase in the proportion of CX3CR1+ cells was associated with a 34% higher OS risk (OR = 1.34, p = 0.003), with a mediation effect accounting for 4.91%, suggesting that the microbiota may promote tumor progression through immune phenotype remodeling." (PMID 41180320, 2025). "The experimental results showed that the CX3CR1 inhibitor significantly suppressed tumor growth and achieved treatment effects similar to the PD‐1 antibody." (PMID 39783838, 2025). "In contrast, a subset of Treg cells infiltrating the tumor tissue exhibited high expression of CX3CR1." (PMID 39783838, 2025). "CX3CR1 up-regulation was detected in splenic and tumor-infiltrating MDSCs across both murine tumor models." (PMID 41280721, 2025). "Once within the tumor, these BMDMs differentiate into CX3CR1+CCR2− TAMs and acquire an M2-like immunosuppressive phenotype, promoting immune evasion." (PMID 41002423, 2025). "Similar to Cx3cr1−/− mice, CX3CR1 knockout in PMN-MDSCs inhibited tumor growth and reduced both total MDSCs and PMN-MDSCs proportions, while M-MDSCs remained unchanged." (PMID 41280721, 2025). "Reports indicate that CX3CR1 exhibits both tumor-promoting and tumor-suppressing effects in oncology, potentially linked to tumor heterogeneity and immune system complexity." (PMID 41267985, 2025). "CX3CR1 is the sole receptor for CX3CL1, and the CX3CL1/CX3CR1 axis has been shown to regulate functions such as inflammatory cell chemotaxis and tumor cell adhesion." (PMID 40145607, 2025). "This relationship highlights the role of CX3CL1 as a key factor that recruits immunosuppressive cells to the tumor site through a CX3CR1-dependent mechanism, thus modulating the tumor microenvironment." (PMID 40051011, 2025). "CX3CR1 sufficiency enhanced tumor cell CCL26 induction; this effect was attenuated by TGF-β1 blockade and reduced in Cx3cr1cKO PMN-MDSCs." (PMID 41280721, 2025). "The PWY.3001‐associated microbiota increases OS risk by inhibiting protective metabolites like cmpf (mediating effect of 35%), while F. plautii promotes tumor progression via CX3CR1 activation on CD14− CD16− protumor monocytes (mediating effect of 4.91%)." (PMID 41180320, 2025). "In contrast, CX3CR1+ microglia at the tumor margin drive tumor invasion via matrix metalloproteinase (MMP)-mediated extracellular matrix remodeling." (PMID 41002423, 2025). "The CX3CL1/CX3CR1 axis has emerged as a key player in the tumor microenvironment of various hematologic malignancies." (PMID 40508161, 2025). "Future studies focused on the CX3CL1‒CX3CR1 axis in the tumor microenvironment, including blockade experiments, are needed to validate these mechanisms." (PMID 40051011, 2025). "Tumor-associated macrophages (TAMs), comprising up to 50% of the tumor mass, are recruited via chemokine axes such as CCL2/CCR2, CX3CL1/CX3CR1, and CXCL12/CXCR4 and adopt an M2-like immunosuppressive phenotype, facilitating immune escape and angiogenesis." (PMID 41002423, 2025).
tumor (continued). "GBM cells and tumor-associated endothelial cells secrete CCL2, which binds to CCR2 on circulating CX3CR1+CCR2+ monocytes, facilitating their transmigration across the blood–brain barrier into the tumor microenvironment." (PMID 41002423, 2025). "Sorted PMN-MDSCs from Cx3cr1fl/flS100a8cre tumor-bearing mice show marked Cx3cr1 reduction at mRNA and surface protein levels (qPCR, flow MFI)." (PMID 41280721, 2025). "Spatial interdependency analyses uncovered microdomain colocalization patterns between TSPAN4+ fibroblasts and CX3CR1+ monocytic derivatives at tumor invasion zones." (PMID 40443671, 2025). "CX3CR1 is a chemokine receptor majorly involved in regulating monocyte chemotaxis and tumor angiogenesis." (PMID 40564200, 2025). "Mechanistically, we show that NK cells are actively recruited to immune-excluded areas upon ICB exposure via the chemokine receptor CX3CR1 to suppress tumor infiltration and antitumor function of CD8+ T cells." (PMID 40530504, 2025). "Previous studies showed that Cx3cr1 expression contributed to macrophage survival in tumor metastasis and was correlated with poor prognosis in human cancers." (PMID 40282557, 2025). "In particular, the CX3CL1–CX3CR1 axis has been implicated in neural tropism, whereby fractalkine-expressing nerves attract CX3CR1+ tumor cells." (PMID 41394398, 2025). "In our study, the presence of CX3CR1+ MDSCs in the tumor microenvironment, likely driven by CX3CL1, appeared to contribute to this immunosuppression, potentially facilitating tumor progression." (PMID 40051011, 2025). "Key microglia-associated genes, including TREM2 and CX3CR1, regulate immune suppression, tumor proliferation, and invasion, while IL-1β and TNF-α contribute to tumor-promoting inflammation." (PMID 40076502, 2025). "CX3CL1 can induce the migration of oral cancer cells in a dose-dependent manner, and CX3CL1-positive nerves can attract CX3CR1-positive tumor cells, thereby promoting the development of perineural invasion (PNI) in OSCC patients." (PMID 41445742, 2025). "In an in vivo study, CAR-T cells expressing CX3CR1 demonstrated enhanced migration towards tumor cells producing CX3CL1, leading to tumor regression." (PMID 41200177, 2025). "Their study also revealed that activation of the fractalkine-CX3CR1 axis inversely correlates with increased cell proliferation and tumor differentiation in HCC, potentially reducing survival rates." (PMID 40051011, 2025). "Single-cell transcriptomics analysis of OC tumor tissues collected from different metastatic sites revealed that CX3CR1+ TAMs are predominantly present in the primary tumors and peritoneal metastatic sites." (PMID 41341850, 2025). "Considering the tumor-promoting trend and high inflammation parameters in Closure CX3CR1high patients, we used flow cytometry to classify the phenotypes of CX3CR1+ cells." (PMID 38433196, 2024). "Other studies link the upregulation of the FKN/CX3CR1 axis in tumorigenesis with enhanced metastasis and invasion, although in some cases it simultaneously promotes tumor infiltration with effector immune cells." (PMID 39125578, 2024). "With regard to tumor-promoting or immunosuppressive cells, CX3CR1 is reportedly expressed by Tregs, MDSCs, and TAMs; therefore, we analyzed CD3 expression in Tregs, CD14 and CD163 expression in M-MDSCs and TAMs, and LOX-1 expression in PMN-MDSCs." (PMID 38433196, 2024). "The simultaneous co-expression of mFKN and CX3CR1 in cancer cells leads to cell adhesion, which significantly impedes cellular migration and tumor spread." (PMID 38731899, 2024). "Third, AA additionally inhibits the expression of genes coding for chemokine and cytokine receptors essential for anti-tumor NK cell functions, notably CX3CR1 and CXCR3, which are similarly downregulated in TANK compared to normal NK cells." (PMID 39563446, 2024).
tumor (continued). "In the context of OAC, CCR1, CCR5, and CX3CR1 were identified as key drivers of erroneous T cell migration to the omentum at the expense of effective anti-tumour immunity." (PMID 38672174, 2024). "When CX3CR1 binds to CX3CL1, multiple pathways are activated that cause tumor and immune cells to migrate, invade, and metastasize, ultimately leading to angiogenesis." (PMID 38433196, 2024). "The upregulated expression of FKN leads to the increased accumulation of CX3CR1+ immune system cells in tumor tissue and significantly increases local CX3CR1 density with the possibility of CX3CR1 induction in tumor cells." (PMID 38731899, 2024). "Expression of CX3CR1 was significantly elevated among CAR+T cells versus endogenous T cells in tumor tissues (mean 83% vs 10.8%, p=0.0268)." (PMID 38754916, 2024). "Here, we demonstrated that CX3CR1+ macrophages exhibit anti-tumor effects, displaying a pro-inflammatory phenotype." (PMID 38658971, 2024). "Some monocyte populations, such as patrolling monocytes, which are recruited to the tumor through CX3CR1, have shown to promote antitumor immunity such as activating NK cells." (PMID 38716730, 2024). "The benefit of targeting CX3CR1–CX3CL1 is that they are the only ligand receptor to each other and inhibition of CX3CL1–CX3CR1 signaling can suppress tumor cell migration directly in case that tumor cells express CX3CR1." (PMID 38786066, 2024). "Concomitantly CD11b+CX3CR1+ (e.g., clusters 5, 7, and 15) monocyte-derived macrophage populations, and MHC class II+CD11b+Ly6C+ cells (cluster 15), potentially consisting of tumor-associated macrophages, increased." (PMID 39481389, 2024). "CX3CR1 is a chemokine receptor that, by influencing monocyte chemotaxis and tumor angiogenesis, can alter the tumor immune microenvironment, thereby affecting tumor development and immune responses." (PMID 38566827, 2024). "CX3CL1/CX3CR1 has a tumor-suppressive activity by recruiting antitumoral immune cells such as NK and T cells into the tumor microenvironment to control tumor growth." (PMID 39290304, 2024). "According to a study published in Nature, administering anti-PD-1 to tumor-bearing mice increased the frequency and clonality of the T cell receptor belonging to the CX3CR1+CD8+ subset." (PMID 39273452, 2024). "Amanda’s study showed that ITGAL promotes Cx3cr1 expression, cx3cl1-mediated migration and Ccl5 expression in microglia, thereby promoting microglial infiltration and tumor formation." (PMID 39605903, 2024). "We have identified CX3CR1 modulation and/or tumour chemokine profile remodelling as approaches to skew NK cell migration towards tumour." (PMID 38369570, 2024). "The CX3CL1/CX3CR1 axis has an anti-tumor effect by acting as a chemotactic cytokine recruiting immune cells such as NK and T cells, but the complex can also activate pro-tumoral responses." (PMID 39594776, 2024). "We found that CX3CR1+ macrophages enhanced the expression of the corresponding target tumor inhibitory genes, such as BTG2, EGR2, ERG3, NR0B1, and SDC4, on NR5A1+ tumor cells." (PMID 38658971, 2024). "To identify the relationship between increasing VLSs and CX3CL1, we analyzed the histopathological locations of increasing CX3CL1+ and CX3CR1+ structures in MOC2CX3CL1 tumor tissues." (PMID 38775151, 2024). "Our findings suggest a potential inhibitory role of CX3CR1+ macrophages in tumor growth within the SF1 lineage of PitNETs." (PMID 38658971, 2024). "This axis interacts with and recruits TAMs and MDSCs in tumor sites; therefore, these cells express CX3CR1 in tumors, as observed in our study." (PMID 38433196, 2024). "To investigate the regulatory role of CX3CR1+ macrophages on NR5A1+ tumor cells, we co-cultured PitNETs isolated CX3CR1+ or CX3CR1− macrophages with autologous CD45− tumor cells." (PMID 38658971, 2024). "In contrast, inhibitors of AKT and CX3CR1 synergistically reduced Ki67+ cells, consistent with the effects on tumor growth." (PMID 38781024, 2024).